CYP3A4 (cytochrome P450 family 3 subfamily A member 4)
Diseases named in the same sentence as CYP3A4 in open-access papers (continued):
Sharing a sentence is not in itself a finding about the gene and the disease.
Thrombocytopenia (10 papers, 2015 to 2026). A reduction in the number of circulating thrombocytes. "Another variant rs4986910 (CYP3A4, T > C) correlated with thrombocytopenia grade 3–4, before and after correction for relevant covariates (p = 0.012, OR 5.61 and p = 0.025, OR 4.99 respectively)." (PMID 25881102, 2015). "We did observe, however, a significant association between rs4986910 (1331 T > C) in CYP3A4 and thrombocytopenia." (PMID 25881102, 2015). "Likewise, increased risk of thrombocytopenia was associated with rs4986910 (CYP3A4, T > C; p = 0.025, OR = 4.99, 95% CI = 1.22-20.31)." (PMID 25881102, 2015). "In accordance with this observation an increased occurrence of peripheral neuropathy and also thrombocytopenia has been observed in patients who received concomitantly bortezomib and itraconazole, another potent CYP3A4 inhibitor." (PMID 30123673, 2018). "Furthermore, the liver enzymes CYP3A4 and CYP3A5 are also trapped in the drug metabolism of T-DM1, and patients with mutations in these two genes are susceptible to AEs associated with T-DM1, especially thrombocytopenia." (PMID 38741766, 2024). "We hypothesize that through the inhibition of CYP2B6, CYP2C9, CYP2C9, CYP2C19, and CYP3A4, Schisandra chinensis preparations increased the concentration and side effects of bupropion (thrombocytopenia and generalized arthralgia), amitriptyline (delirium), and fluoxetine (dysuria)." (PMID 37829299, 2023).
type 2 diabetes (10 papers, 2017 to 2025). "Hence, the present study aims to characterize the activity of CYP1A2, CYP2B6, CYP2C9, CYP2C19, CYP2D6, CYP3A4/5, and P-glycoprotein (P-gp) pump in patients with type 2 diabetes (T2DM)." (PMID 32337164, 2020). "Similarly, a patient with type 2 diabetes may show diminished CYP3A4 activities and decreased clearance of CYP3A substrates due to downregulation of CYP3A4 expression secondary to chronic inflammatory conditions." (PMID 34575542, 2021).
vitamin D deficiency (10 papers, 2014 to 2024). A nutritional condition produced by a deficiency of VITAMIN D in the diet, insufficient production of vitamin D in the skin, inadequate absorption of vitamin D from the diet, or abnormal conversion of vitamin D to its bioactive metabolites. "Taken together, screening for vitamin D deficiency is appropriate in many chronic conditions and in patients treated with strong CYP3A4-inducing drugs." (PMID 39125269, 2024). "A recurrent gain-of-function variant in CYP3A4 has been associated with vitamin D rickets, and induction of CYP3A4 by rifampin and other medications can similarly lead to vitamin D deficiency as a side effect." (PMID 36990163, 2023). "Serum 25OHD levels will also be low in subjects with VDDR type III, in whom gain of function mutation in CYP3A4 leads to vitamin D deficiency through accelerated inactivation of vitamin D metabolites." (PMID 33660084, 2021). "Importantly, CYP3A4 mutations or drug-induced excess CYP3A4 activity have recently been linked to vitamin D deficiency and vitamin D–dependent rickets type 3, with affected individuals demonstrating greatly accelerated inactivation of vitamin D metabolites." (PMID 38676447, 2024). "In case of vitamin D deficiency, CYP3A4 may potentially get shunted for vitamin D hydroxylation, to maintain the levels of 25OH vitamin D, reducing availability of CYP3A4 for statin metabolism." (PMID 32292293, 2020). "With vitamin D deficiency, CYP3A4 may potentially get shunted for vitamin D hydroxylation, in an effort to maintain levels of 25 (OH) vitamin D, reducing availability of CYP3A4 for statin metabolism, thereby increasing serum statin levels and subsequent statin toxicity." (PMID 24586424, 2014).
Anxiety (9 papers, 2014 to 2025). Intense feelings of nervousness, tension, or panic often arise in response to interpersonal stresses. "NMVr, due to the ability of ritonavir to inhibit CYP3A4, has an increased risk of drug–drug interactions leading to neuropsychiatric adverse events such as anxiety, insomnia, and cognitive dysfunction." (PMID 40142695, 2025). "Patients receiving NMVr should undergo neuropsychiatric monitoring, particularly those with preexisting psychiatric conditions, as ritonavir can disrupt neurotransmitter metabolism via CYP3A4 inhibition, exacerbating anxiety and sleep disturbances." (PMID 40142695, 2025). "By inhibiting CYP3A4, ritonavir can elevate the plasma concentrations of concomitantly administered medications, increasing the likelihood of neuropsychiatric ADRs such as anxiety, delirium, and sleep disturbances." (PMID 40142695, 2025).
breast tumor (9 papers, 2004 to 2025). "Genetic polymorphism and expression of CYP3A1 or CYP3A4 in breast tumor tissues have been reported to be potentially useful factors for the prediction of treatment responses to chemotherapy." (PMID 33628298, 2021). "Reports suggest that upregulation of CYP3A4 is seen in 80% of breast tumors and can be used to identify tumor response in different treatments." (PMID 38081857, 2023). "A CYP3A4 knockdown or biguanide inhibition activates AMPKα, promotes autophagy, and prevents breast tumor formation." (PMID 36359206, 2022). "By contrast, according to other data (obtained by immunoblotting), CYP3A4 expression is lower in breast tumor tissue compared to the morphologically normal adjacent tissue." (PMID 36359206, 2022). "For instance, low CYP3A4 expression in breast tumors resulted in a better response to docetaxel, while high CYP3A expression in osteosarcoma tumors predicted metastasis and poor prognosis." (PMID 23344024, 2012). "Moreover, the epoxygenase activity of CYP3A4 on arachidonic acid (AA), which is required for breast tumor formation, promotes the activity of the mitochondrial electron transport chain, which can be inhibited by metformin." (PMID 39754188, 2025). "In breast tumours however, the WT1-expressing tumours are mainly associated with a mesenchymal phenotype and high levels of CYP3A4: therefore, their cells not only respond poorly to taxane, but they are also more likely to invade the blood vessels and metastasise." (PMID 28345629, 2017). "In conclusion, the detected presence of CYP3A4 and CYP2C9 in breast tumours offers the possibility of intratumoral turnover of ifosfamide." (PMID 14970873, 2004). "In conclusion, the presence of two important ifosfamide catalysts CYP3A4 and CYP2C9 in breast tumours suggests that its local turnover could be of importance in cancer therapy." (PMID 14970873, 2004).
endometrial cancer (9 papers, 2009 to 2024). Primary or metastatic malignant neoplasm involving the endometrium (mucous membrane that lines the endometrial cavity). "The second highest scoring bi-clique observed here was the main effect of CYP3A4*1B genotypes, which are associated with increased catecholestrogen formation, and would therefore be expected to be associated with increased endometrial cancer risk." (PMID 19287484, 2009). "In addition, CYP3A4*1B (currently named CYP3A4*1.001, rs2740574) is associated with a 3-fold higher risk of endometrial cancer in TAM-treated BC patients." (PMID 34899282, 2021). "Overexpression of CYP3A4 in a malignant tissue compared to a respective normal tissue is usually associated with predisposition to breast and ovarian cancers and may play an important role in the initiation of endometrial cancer." (PMID 36359206, 2022). "Their findings suggested higher PXR and CYP3A4/7 expression in endometrial cancer tissues with lower ER-α status." (PMID 24690092, 2014). "Later studies suggest that downregulation of PXR expression may be oncogenic in hormone-dependent breast and endometrial cancers by reducing estrogen metabolism via CYP3A4; thus, higher estradiol concentrations contribute to carcinogenesis." (PMID 24690092, 2014). "In endometrial cancer, CYP3A4 and MDR1 activity were induced by the activation of SXR." (PMID 23443531, 2013). "Another study found that CYP3A4 and CYP3A7 mRNA expression was low in normal endometrium, but was significantly upregulated in endometrial cancer tissues." (PMID 31309254, 2019). "Moreover, ligands of PXR enhance PXR-mediated transcription in a ligand- and promoter-dependent manner, resulting in differential regulation of the expression of PXR’s individual target genes, especially CYP3A4 and MDR1, in endometrial cancer cells." (PMID 36359206, 2022).
gastric cancer (9 papers, 1998 to 2023). A primary or metastatic malignant neoplasm involving the stomach. "Interestingly, a new report showed that elevated expression of CYP3A4 could be associated with the progression of chronic atrophic gastritis to gastric cancer and might predict poor prognosis." (PMID 33659048, 2021). "Gastric cancer patients who were CYP3A4*22 carriers had higher rates of toxicity (58%) compared to non-carriers who were homozygous for CYP3A5*3 (41%) and non-carriers heterozygous for CYP3A5*3 (17%)." (PMID 35174070, 2021). "We have observed that HIF-2α modulates the recruitment of pregnane X receptor (PXR) to the PXR response element in the CYP3A4 (cytochrome P450 3A4) gene promoter region in gastric cancer BGC-823 cells (Jiuda Zhao, unpublished data)." (PMID 25590810, 2015). "A phase 1 study of 6 Japanese patients with advanced/recurrent gastric cancer (JapicCTI‐142420) found that the PK and safety profiles of napabucasin were not affected by paclitaxel, a CYP2C8 and CYP3A4 substrate." (PMID 34107166, 2021). "In addition to ERBB2 and PERLD1, the TRAC analysis also identified five novel genes, CYP3A4, ENAH, MMP9, PTPRA, and OSMR, which have not been reported as gained and overexpressed in gastric cancer before." (PMID 20187983, 2010).
osteosarcoma (9 papers, 2008 to 2024). A usually aggressive malignant bone-forming mesenchymal neoplasm, predominantly affecting adolescents and young adults. "The kinetics of CYP3A4 up-regulation (48 hour post-treatment) by SXR activators matches with previously reported timing for its induction by SXR activators in osteosarcoma cells, where its activation induces genes involved in bone homeostasis." (PMID 19123943, 2009). "Osteosarcoma is the most frequent bone tumour in children, and CYP1A1/2, CYP1B1, and CYP3A4/5 expressions have been commonly found in primary biopsies, the latter positively correlating with metastatic disease." (PMID 38473371, 2024). "Using standard inmunohistochemical methods, CYP3A4/CYP3A5 enzymes have been previously identified in various types of malignant tumors, including soft tissue sarcomas and osteosarcoma." (PMID 24699256, 2014).
ovarian carcinoma (9 papers, 2002 to 2024). A malignant neoplasm originating from the surface ovarian epithelium. "Additional follow-up is warranted to confirm the association between this CYP3A4 variant and risk of ovarian cancer, and ideally these studies should be performed in different racial groups." (PMID 19127255, 2009). "In conclusion, we have identified a possible association between an SNP (rs2740574) in the key oestrogen-metabolizing gene CYP3A4 and ovarian cancer risk." (PMID 19127255, 2009). "Additionally, reports have shown that the CYP3A4 rs2740574 variant is inversely associated with ovarian cancer morbidity." (PMID 38001897, 2023). "Moreover, CYP3A4 rs2740574 was associated with worse overall survival in patients with ovarian cancer treated with platinum and taxane drugs." (PMID 38001897, 2023). "CYP3A4 encodes a key enzyme in oestrogen metabolism and our finding between rs2740574 and risk of ovarian cancer suggests that this pathway may be involved in ovarian carcinogenesis." (PMID 19127255, 2009). "Given that exposure to oestrogen is associated with the risk of ovarian cancer it is plausible that the CYP3A4 rs2740574 variant might influence ovarian cancer development through decreased expression of the gene and thus reduced metabolism of oestrogen." (PMID 19127255, 2009). "The association between this CYP3A4 variant and risk of ovarian cancer was consistent across these two racial/ethnic groups in the combined existing and follow-up data: ORhom in Blacks=6.82 (95% CI 0.73–63.86, P=0.093) and ORhom in Whites=2.40 (95% CI 0.67–8.68, P=0.18)." (PMID 19127255, 2009). "Further studies should focus on the presence and kinetic properties of CYP3A4 and other drug-inactivating enzymes in other cancers that are treated with CYP3A4 substrates such as breast, lung and ovary cancers." (PMID 12237780, 2002). "Importantly, CYP3A4 is also involved in the metabolism of 60% of pharmaceutical drugs, together with chemotherapy used for ovarian cancer treatment, such as docetaxel and paclitaxel." (PMID 38001897, 2023). "A later study investigated the presence of taxane-metabolizing enzymes in ovarian cancer and found that CYP3A4 is expressed at very low levels in ovarian cancer, while CYP3A5 and CYP2C8 were expressed in the majority of ovarian tumors, regardless of histologic type, stage, or grade." (PMID 31309254, 2019). "Other CYP3A4 genetic variants had no impact on ovarian cancer susceptibility." (PMID 38001897, 2023). "Moreover, lower expression of CYP3 enzymes, particularly CYP3A4, may influence the survival of ovarian cancer patients as they may be ineffective in metabolizing or activating cyclophosphamide and doxorubicin, the standard drugs used for the treatment of ovarian cancers." (PMID 38001897, 2023). "In contrast, high mRNA expression of CYP2A6, CYP2C9, CYP2J2, CYP3A4, CYP3A5, CYP3A7, and CYP3A43 connoted a good prognosis for ovarian cancer patients." (PMID 38001897, 2023). "In contrast, high and more frequent CYP3A4 protein expression was found in both normal ovaries and primary ovarian cancer, although its differential expression was not significant." (PMID 38001897, 2023). "Indeed, in epithelial ovarian cancer (OC) cells, PXR agonists, phthalate and P5, have been shown to induce the expression of CYP3A4 by binding to the CYP3A4 promoter, whereas paclitaxel and cisplatin increased the MDR1 expression and PXR binding to the MDR1 promoter." (PMID 39682707, 2024). "Similarly, extremely low levels of CYP3A4 mRNA were identified in primary ovarian cancer samples, while no CYP3A4 protein was expressed." (PMID 38001897, 2023).
Sepsis (9 papers, 2012 to 2025). Sepsis is defined as life-threatening organ dysfunction caused by a dysregulated host response to infection. "CYP3A4 rs35599367 polymorphism presented a significant association with nephrotoxicity, sepsis, seizures and psychosis." (PMID 36246675, 2022). "Third, we detected drug interaction signals and found an increased risk of sepsis when ADCs were co-administrated with colony-stimulating factors, proton pump inhibitors, H2-receptor antagonists, and CYP3A4/5 strong inhibitors." (PMID 36467034, 2022). "Co-administration of ADCs with colony-stimulating factors, proton pump inhibitors, H2-receptor antagonists, or CYP3A4/5 inhibitors showed to synergistically increase the risk of sepsis-related toxicities." (PMID 36467034, 2022). "G-CSF/GM-CSF, proton pump inhibitors, H2-receptor antagonists, and CYP3A4/5 inhibitors may synergistically increase the risk of sepsis with ADCs." (PMID 36467034, 2022). "A significant association exists between CYP3A4 rs35599367 polymorphism with neurotoxicity and nephrotoxicity and between PPARA rs4253728 and rs4823613 polymorphism with sepsis in Pakistani liver transplant recipients taking tacrolimus." (PMID 36246675, 2022). "We then included the most common CYP3A4/5 strong inhibitors which contain protease inhibitors, imidazole and triazole derivatives, and macrolides, and analyzed sepsis-related toxicities when ADCs were combined with the previously listed CYP3A4/5 inhibitors." (PMID 36467034, 2022). "Since most of the ADCs are metabolized by the CYP3A4/5 enzyme, the safety signal for sepsis was elevated when ADCs were co-administrated with CYP3A4/5 strong inhibitors." (PMID 36467034, 2022). "DDI signals were detected for sepsis (Ω025 0.28) and fungemia (Ω025 0.02) for the combination of ADCs and CYP3A4/5 inhibitors." (PMID 36467034, 2022). "In the PCI mouse model of sepsis the expression and activity of the murine homolog for CYP3A4 was found primarily diminished in acute phase response to sepsis, but increased during recovery from sepsis in surviving animals." (PMID 30873161, 2019). "In particular, CYP3A4 is known to be downregulated during inflammation and sepsis." (PMID 36899906, 2023). "Sepsis safety signals for ADCs and CYP3A4/5 strong inhibitors combination therapy." (PMID 36467034, 2022). "Second, we analyzed the drug–drug interaction signals for sepsis between ADCs and granulocyte colony-stimulating factor (G-CSF) or granulocyte-macrophage colony-stimulating factor (GM-CSF), proton pump inhibitors, H2-receptor antagonists, and CYP3A4/5 strong inhibitors." (PMID 36467034, 2022). "First, we analyzed the safety signal for sepsis when ADCs were co-administrated with the granulocyte colony-stimulating factor (G-CSF) or granulocyte-macrophage colony-stimulating factor (GM-CSF), proton pump inhibitors, H2-receptor antagonists, and CYP3A4/5 strong inhibitors." (PMID 36467034, 2022). "Because of the similarity between mouse-CYP3A11 and human-CYP3A4, CYP3A11 expression and activity were explored with some intestinal drug transporters in mouse models of I/R (acute and chronic) and sepsis." (PMID 30991873, 2019).
hypothyroidism (8 papers, 2018 to 2025). Abnormally low levels of thyroid hormone. "Rodents and humans with hypothyroidism have decreased CYP3A4 activity, which affects drug metabolism." (PMID 39901894, 2025). "Additional risk factors include hepatic or renal impairment, co-medication with CYP3A4 inhibitors, co-medication with SLCO1B1 inhibitors, female gender, old age (≥ 65) or hypothyroidism." (PMID 31196067, 2019). "Apalutamide, a potent CYP3A4 inducer, is thought to stimulate the hepatic activity of UDP-glucuronyl transferase via activation of the PXR nuclear receptor, leading to increased clearance of T4 with a decrease in its systemic concentration and hypothyroidism." (PMID 40905521, 2025). "Due to the possibly reduced CYP3A4 enzymes and MAO in hyper- and hypothyroidism, serum concentration levels of triptans could be higher since they are metabolized by these enzymes." (PMID 38347465, 2024).
kidney transplant (8 papers, 2021 to 2026). A surgical procedure in which one or both kidneys from a donor are implanted into a recipient. "This meta-analysis aims to evaluate the association between CYP3A4*22 polymorphism and the dose-adjusted trough concentration (C0/D) of Tac in adult kidney transplant patients." (PMID 37564175, 2023). "Interestingly, a previous study conducted among Jordanian kidney transplant recipients revealed a correlation between genetic variations in both CYP3A4 and CYP3A5 enzymes and tacrolimus blood levels among renal transplant recipients." (PMID 36042898, 2022). "Moreover, we studied the potential impacts of CYP3A4 and CYP3A5 genotypes on post-kidney transplant complications such as delayed graft function, rejection, BK infections, viral acute graft pyelonephritis, and suspected calcineurin inhibitor nephrotoxicity." (PMID 38610733, 2024).